INS (insulin)
Diseases named in the same sentence as INS in open-access papers (continued):
Sharing a sentence is not in itself a finding about the gene and the disease.
diabetes (continued). "The oxidative stress may play a key role in the late complications of diabetes through impaired neuronal insulin signaling, activation of advanced glycation end products (AGE/RAGE), polyol and protein kinase C (PKC) pathways, leading to increased brain inflammation and neurodegeneration." (PMID 33918576, 2021). "The Diabetes Mellitus Insulin Glucose Infusion in Acute Myocardial Infarction 2 (DIGAMI-2) trial comprised 1253 patients of whom 947 were randomly assigned to insulin-based or conventional glucose control at hospital discharge after receiving 24 h of insulin–glucose infusion in hospital." (PMID 34158057, 2021). "Diabetes mellitus (DM) is a metabolic disorder that involves persistent hyperglycemia, resulting from defects in insulin production, insulin action, or both." (PMID 34805411, 2021). "Moreover, novel diabetes technologies, including continuous glucose monitoring and (hybrid) closed-loop systems generate complex glucose and insulin data, which patients need to evaluate and act on accordingly, increasing the information burden and cognitive demand of T1DM self-management." (PMID 36994333, 2021). "Diabetes mellitus (DM) is a metabolic disorder characterized by chronic low-grade inflammation in the pancreatic islets and impaired insulin secretory capacity." (PMID 34502451, 2021). "A study reported that relatives of patients with diabetes and a high BMI were associated with insulin resistance, and that this was consistent with the independent association of being the relative of a patient with diabetes, a high BMI, and low QUICKI (low insulin sensitivity)." (PMID 34442147, 2021). "However, insulin-treated diabetes was not identified as an independent risk factor for higher mortality in the 1st (HR 1.29; 95% CI 0.97–1.72, p = 0.084) and 3rd years (HR 1.21; 95% CI 0.98–1.49; p = 0.079) after multivariable adjustment." (PMID 34207517, 2021). "Type 2 diabetes mellitus (DM) is a complex syndrome characterized by chronic hyperglycemia as a consequence of a disorder of insulin secretion, insulin resistance/action, or combination of both of these factors." (PMID 34853597, 2021). "However, impaired/absent insulin signaling may lead to metabolic disorders such as type 2 diabetes mellitus (T2DM), a significant public health concern due to its pandemic occurrence and several comorbidities and dramatic medical costs." (PMID 34072220, 2021). "Further evidence that pancreas-derived insulin is not the predominant retinal IR ligand includes the finding that retinal insulin content does not vary with feeding and fasting or from insulin-deficient diabetes, in spite of very low serum levels and high retinal IR-ß activity in fasted animals." (PMID 33915127, 2021). "Of note, lowering the level of CD44 variant (CD44v), which can steady the system Xc–, increases insulin secretion and contributes to the amino acid transport regulated by L-type amino acid transporter LAT1 in pancreatic β cells; thus guiding a new therapeutic target in diabetes." (PMID 34307381, 2021). "Accordingly, findings suggest that CDCA incorporation with islets have direct biological effects on islet functions, insulin release, and glycemic response, and can also exert significant anti-inflammatory effects, potentially further improving the islets insulin release and diabetes treatment." (PMID 34572086, 2021). "Type 2 diabetes mellitus (T2 DM) is a metabolic disorder characterized by variable degrees of insulin resistance, impaired insulin secretion, and increased glucose production." (PMID 34795701, 2021). "First, considering that insulin therapy in clinical practice is often initiated in the later treatment course of diabetes due to clinical inertia, most patients may have been treated with multiple GLAs and had vascular complications at the initiation of basal insulin." (PMID 33602950, 2021).
diabetes (continued). "However, evidence from pre-clinical and limited clinical trials indicate that insulin and agents that promote insulin signaling could reduce neuropathology and boost cognition in diabetes and LOAD." (PMID 34577590, 2021). "Also, regular physical exercise and avoidance of obesity will reduce both glucose and insulin levels and may be beneficial in both normal people and those with diabetes." (PMID 33708999, 2021). "Diabetes Mellitus (DM) is a well characterised metabolic disease that results in defects in insulin output i.e. insulin secretion (type-1 diabetes) and insulin action (type-2 diabetes) or both." (PMID 34238110, 2021). "Diabetes mellitus (DM) is a group of metabolic disorders characterized by hyperglycemia due to insufficient insulin secretion, insulin resistance, or both." (PMID 33939302, 2021). "In addition, novel diabetes technology such as continuous glucose monitors, electronic decision support systems and automated insulin delivery systems might be beneficial to better control SIHG and provide more outcome data in the near future." (PMID 34065762, 2021). "In addition to language modification like change “how my diabetes medications (pills, injectables and/or insulin) work in my body” to “how diabetes medications (pills, injectables and/or insulin) reduce blood sugar in my body” to make semantic expressions clearer." (PMID 33472648, 2021). "Cardiac preconditioning is attenuated by diabetes, and the loss of cardioprotective effects may be caused by the inhibition of insulin signaling whereas the effects of Leu seem not to largely depend on the insulin-related mechanisms." (PMID 34801078, 2021). "Hyperglycemia, insulin resistance, elevated insulin and insulin-like growth factor-1 (IGF-1) levels, inflammatory cytokines, dyslipidemia, increased leptin, and decreased adiponectin have been attributed to the increased risk of cancer in patients with diabetes." (PMID 34830886, 2021). "Diabetes mellitus (DM) is a group of metabolic disorders characterized by the elevated levels of glucose in the blood and insufficient secretion or action of endogenous insulin." (PMID 34622023, 2021). "Finally, Namayanja and Janeja examined the University of California, Irvine, Diabetes Data Set to derive clusters of behavior patterns correlating to insulin dosage and blood glucose levels to determine at which specific time periods people living with T2D had more imminent needs." (PMID 34783668, 2021). "Moreover, high insulin concentrations can suppress lipolysis and stimulate glucose uptake that could lead to developing diabetes." (PMID 33892738, 2021). "Pancreas transplant remains the best option of treatment to achieve long-term physiological euglycemia and insulin independence for patients with labile diabetes mellitus (DM) such as type 1 DM (T1DM)." (PMID 34702876, 2021). "However, it should be noted that a significant overlap between diabetes, obesity, insulin and hypoglycemic agents on cancer outcome could be a major cause of bias in this study." (PMID 34690923, 2021). "Therefore, more effort is needed to improve TIR in younger children by increasing parents’ diabetes education, refining insulin treatment, or using more advanced technological systems such as closed-loop control, which reduces the occurrence of severe hypoglycemia." (PMID 34836124, 2021). "However, when the analysis was further adjusted for insulin sensitivity, the association of reduced clearance with incident diabetes was no longer significant, consistent with the current results in MILES." (PMID 34206745, 2021). "Usually, insulin is prescribed to patients with a longer diabetes duration, worse glycemic control, more advanced disease stage and beta-cell dysfunction with failure of prior diabetes drugs, more cardiac, renal, and hepatic comorbidities, advanced cancer, infections, or acute conditions." (PMID 34774054, 2021).
diabetes (continued). "This occurs in the early pre-diabetes stage and is characterized by three main mechanisms: (i) the first is hyperglycemia; (ii) the second is elevated free fatty acid levels; (iii) the third is high amylin levels, which is co-secreted with insulin and induces β-cell apoptosis." (PMID 34959658, 2021). "Date of diabetes diagnosis for subsequent calculation of duration of diabetes (month and year will be recorded when the exact date is unknown), current insulin regimen, insulin dosing, HbA1c measurements in previous 6 months, and co-morbidities will be recorded from electronic medical records." (PMID 34900845, 2021). "MIDATs are capable of providing a timestamp on collected images and other data input and may potentially serve as novel and powerful tools in diabetes management by integrating image-based dietary intake with insulin dosing in real-time, empowering PWD to enhance their glycemic control." (PMID 33918343, 2021). "Diabetes mellitus (DM) is a metabolic chronic disease characterized by hyperglycemia (high levels of glucose in the blood), which results from defective insulin secretion, defective insulin action, or both." (PMID 34502144, 2021). "Data indicate that vaspin may be a new drug designed to treat diabetes due to its insulin-sensitizing effect in WAT and inhibitory properties on gene expression associated with insulin resistance, as well as its stimulatory effect on insulin secretion." (PMID 34359881, 2021). "However, we also included individuals with apparently normal serum K at baseline but who nonetheless were at a higher risk for hyperkalemia, such as persons with diabetes mellitus who were not taking insulin and transplant recipients on tacrolimus." (PMID 34444838, 2021). "Hyperuricemia could come from this hyperinsulinism by two ways: Insulin stimulates uric acid reabsorption from the proximal convoluted tubule and the lactic acid produced during diabetes reduces the renal tubular secretion of uric acid through competitive inhibition of uric acid on its receptor." (PMID 35018210, 2021). "Astragalus polysaccharide is a monomer component extracted from the TCM of Huangqi (Radix astragali mongolici), which could improve plasma glucose, insulin resistance and secretion, and the complication of diabetes mellitus with promising effects in recent years." (PMID 34699323, 2021). "Diabetes mellitus (DM), a significant world health problem, is a metabolic disease, which occurs due to a defect in insulin release and or insulin resistance." (PMID 35222988, 2021). "Numerous scientific evidences have revealed that flavonoids may contribute to prevent or ameliorate the insulin resistance in diabetes by their ability to modulate the insulin signaling pathway in classical target tissues such as liver, muscle, and adipose tissue." (PMID 34208379, 2021). "Diabetes mellitus (DM) is one of the commonest metabolic disorder which is characterized by having persistent hyperglycemia due to the abnormalities in insulin secretion or resistance to the insulin action." (PMID 34394276, 2021). "Worse, many individuals who have been users of insulin pump therapy for years are denied coverage for this therapy when failing to meet the C-peptide or beta cell antibody standards when aging into Medicare, significantly disrupting their ability to successfully manage diabetes." (PMID 34077674, 2021). "In diabetes diagnosis, researchers used a patient’s diabetes history and physical examination results such as plasma glucose concentration, diastolic blood pressure, body mass index, age, weight, diet, insulin, water consumption, blood pressure, sex, etc. as input to the machine learning algorithms." (PMID 34574055, 2021).
diabetes (continued). "According to the American Diabetes Association’s Standards of Medical Care in Diabetes—2020, basal insulin including intermediate-acting human insulin (IAHI) and long-acting insulin analogue (LAIA), is suggested for patients with type 2 diabetes (T2D) who require initiation of insulin therapy." (PMID 33602950, 2021). "Although the decrease in serum insulin to the levels near normal values might be one of the factors to compensate deleterious effects of diabetes, however, the reason for high levels of FGF21 relation to phenolics and flavonoids as well as glibenclamide needs furder examination." (PMID 34233693, 2021). "Diabetes mellitus (DM) is a metabolic disorder featuring hyperglycaemia and insulin dysregulation, which can influence retinal and cataract development." (PMID 34587923, 2021). "Diabetes mellitus (DM) is a metabolic disease characterized by the presence of chronic hyperglycemia, which results from either weakened insulin secretion or insulin action or both." (PMID 34696776, 2021). "Another study observed that cod liver oil, a well-established source of ω-3 PUFAs improved the blood pressure, but not HbA1C, in insulin-dependent patients with impaired kidney function, indicating that fatty acids can be more effective in diabetes patients with associated hypertension." (PMID 34926582, 2021). "Diabetes mellitus (DM) is a chronic metabolic disease characterized by hyperglycemia resulting from insufficient insulin action." (PMID 34475700, 2021). "Previous studies have reported that statin treatment affects the calcium channel of the pancreatic β-cells by altering insulin secretion or decreasing glucose transporter 4 translocation, leading to hyperglycemia and hyperinsulinemia, which can be related to the development of diabetes." (PMID 34503545, 2021). "In addition, most of these patients may also experience difficulties during nutrition therapy and when measuring the correct insulin dosage, as part of their diabetes management." (PMID 33561956, 2021). "Furthermore, ML355 administration significantly diminished the formation of 12(S)-HETE in isolated human pancreatic islets and augmented insulin response, suggesting that ML355 exerts beneficial effects in the treatment of diabetes, as marked by an impaired insulin metabolism." (PMID 34680034, 2021). "As diabetes progressed (2–5 years to 6–10 years to >10 years), the proportion of participants on only OADs declined (from 85.1% to 76.5% to 57.4%, respectively), and the proportion of those receiving OADs+insulin increased (from 14.1% to 22.5% to 40.8%, respectively)." (PMID 34277959, 2021). "Diabetes (DM, diabetes mellitus) is a complex metabolic disorder which is characterized by hyperglycemia due to insulin insufficiency and/or insulin dysfunction." (PMID 33918576, 2021). "Interestingly, the clinical phenotypes associated with different INS mutations or even with same mutations range from severe neonatal diabetes to mild adult-onset diabetes, or some even without overt diabetes as the time of studies." (PMID 35069438, 2021). "Longitudinal studies using objective sleep tracking are needed in persons initiating insulin pump therapy because a significant amount of time is required to acclimate to the use of the new diabetes technology before sleep may be improved and since self-reported sleep changes are often inaccurate." (PMID 33628834, 2021). "Although in this model we have previously provided evidence that the development of diabetes from prediabetes is related to inflammation and changes in the activation of insulin signaling pathways in the hypothalamus, hyperglycemia may boost inflammation as reported." (PMID 34440853, 2021). "Hence, it was reported that in children with established T1DM and concomitant biopsy diagnosis of coeliac disease over a 10-year period, gluten-free diet significantly improved both weight, height, and BMI adjusted for age, and improved diabetes control by reducing daily insulin doses." (PMID 33803255, 2021).
diabetes (continued). "Insulin glargine is a long-acting analogue of human insulin that has been used to manage hyperglycemia in patients with diabetes mellitus (DM) for nearly 20 years." (PMID 34133466, 2021). "Diabetes mellitus (DM) is a chronic metabolic disorder characterized by an increase in blood glucose levels resulting from pancreatic defects in insulin production, insulin function, or both." (PMID 33921201, 2021). "Diabetes mellitus (DM) is characterized by long-term hyperglycemia resulting from the defect of insulin production and insulin resistance of insulin-responsive tissue and ultimately results in a series of chronic complications." (PMID 34881312, 2021). "Diabetes mellitus (DM) is a chronic disease that is characterized by high blood glucose levels due to the inability to produce adequate amounts of insulin and/or resistance to the hormone’s actions." (PMID 34193056, 2021). "Diabetes mellitus (DM) comprises a group of metabolic diseases characterized by hyperglycemia resulting from a defect in insulin secretion, insulin action, or both." (PMID 33905625, 2021). "Importantly, if harmine family drugs have beneficial effects on insulin sensitivity via adipocytes and autoimmunity, targeting may actually be detrimental for diabetes." (PMID 34335466, 2021). "Given the emerging role of S-acylation in insulin secretion and insulin signalling, it is not surprising that several S-acylation and deacylation enzymes have been linked to these pathways and are of interest in the context of diabetes." (PMID 33784857, 2021). "The purpose of diabetes technologies is to avoid complications of insulin therapy and to give people with DM more autonomy so that their quality of life (QoL) can be improved." (PMID 33759789, 2021). "Diabetes mellitus (DM) encompasses a group of metabolic disorders characterized by hyperglycemia resulting from defects in insulin secretion, insulin action, or both." (PMID 33572602, 2021). "Therefore, oxidative stress may be involved in the progression from prediabetes to diabetes, impairing glucose uptake in muscle and fat cells and decreasing insulin secretion from β-cells." (PMID 34829598, 2021). "In addition, our findings indicate that OCN might act as an endogenous stimulus for insulin signaling and provide insights into treating diabetes and insulin resistance." (PMID 34489478, 2021). "Interestingly, flavonoids have also demonstrated their therapeutic potential for complications associated with diabetes by improving the impaired insulin signaling route in other non-classical targets such as the endothelium, kidney, and brain." (PMID 34208379, 2021). "This further supports the idea that inhibition of PKR by IHZ could alleviate diabetes induced, metabolic impairments and inflammation and fibrosis in the insulin sensitive organs and tissues, such as skeletal muscles, adipose tissue, pancreas, and liver of the diabetic patients." (PMID 34155273, 2021). "Therefore, the timing or dose of insulin treatment in patients with COVID-19 and diabetes may be an urgent public problem that must be addressed to control the development of COVID-19." (PMID 34367067, 2021). "A genetic defect in intrathymic expression of Igf2 is associated with autoimmune diabetes in BBDP (BioBreeding Diabetes Prone) rats, which may contribute to the absence of central T cell self-tolerance to the insulin hormone family." (PMID 34361972, 2021). "In addition, recent data show that NPB may be positively involved in controlling insulin synthesis and secretion as well as promoting brown adipogenesis, which are important targets for therapy in diabetes and obesity." (PMID 34205710, 2021). "More studies are needed to discern the mechanisms implicated in the changes of the inflammatory profile in these mice, which offer an excellent tool to analyze the factors that may differentially regulate hypothalamic insulin signaling leading to prediabetes or diabetes." (PMID 34440853, 2021).